PFKFB3 (6-phosphofructo-2-kinase/fructose-2,6-biphosphatase 3)
Diseases named in the same sentence as PFKFB3 in open-access papers (continued):
Sharing a sentence is not in itself a finding about the gene and the disease.
psoriasis (4 papers, 2012 to 2024). An autoimmune condition characterized by red, well-delineated plaques with silvery scales that are usually on the extensor surfaces and scalp. "Taken together, these data indicate that inhibition of PFKFB3 attenuates the development of an established mouse model of psoriasis." (PMID 22591674, 2012). "3PO, a small molecule inhibitor of PFKFB3, an enzyme that controls a rate-limiting step of glycolysis, prevented the development of T-cell mediated delayed hypersensitivity and imiquimod-induced psoriasis in mouse." (PMID 31057554, 2019). "Macrophages, dendritic cells and B cells are each suspected to contribute to the development of DTH and to the pathogenesis of psoriasis, and their activation may be suppressed by agents that inhibit PFKFB3 and glycolysis." (PMID 22591674, 2012).
renal carcinoma (4 papers, 2019 to 2024). A carcinoma arising from the epithelium of the renal parenchyma or the renal pelvis. "Blocking of PFKFB3 by selective inhibitor PFK-015 or glycolytic inhibitor 2-DG significantly restrained renal cancer cells’ neoplastic potential." (PMID 38622715, 2024). "In view of renal cancer as a metabolic disease, PFKFB3 mediated glycolytic pathways should affect RCC development and progression." (PMID 38622715, 2024). "As a key glycolysis regulator, PFKFB3 could promote renal cancer cell proliferation and migration in vitro." (PMID 38622715, 2024). "Experimental assays further verified that PFKFB3 could promote renal cancer cell proliferation and migration in vitro, confirming its oncogenic potential in tumor progression." (PMID 38622715, 2024). "Therefore, glucose metabolism can regulate the expression of PD-L1 through the EGFR/ERK/c-Jun pathway in renal cancer, and elevated PD-L1 can also regulate glycolysis by improving the expression of PFKFB3." (PMID 33462221, 2021).
thyroid cancer (4 papers, 2019 to 2023). "Our research has proved that in thyroid cancer, PFKFB3 is the main substrate for Aurora-A to function as an oncogene." (PMID 36990998, 2023). "In summary, our study uncovered the prognostic value of Aurora-A expression in thyroid cancer and a new carcinogenic mechanism: Aurora-A can increase PFKFB3-mediated glycolysis to activate the MAPK and AKT pathways." (PMID 36990998, 2023). "The supplementation of exogenous ATP in PFKFB3 knockdown thyroid cancer cells can effectively restore the tumor suppressive effect." (PMID 36990998, 2023). "Moreover, we analyzed factors that determined thyroid cancer cell response to Alisertib and elucidated the effects of Aurora-A mediated PFKFB3 phosphorylation on glycolysis and biological behavior in thyroid cancer cells." (PMID 36990998, 2023). "However, it remains unclear what role PFKFB3 plays in thyroid cancer." (PMID 36990998, 2023).
type 2 diabetes (4 papers, 2016 to 2025). "Significantly, PFKFB3/iPFK2 is involved in the effect of rosiglitazone, one of the only two currently prescribed medicines as insulin-sensitizers for the treatment of type 2 diabetes, on suppressing intestinal inflammation." (PMID 27387960, 2016). "Indeed, PFKFB3-mediated metabolic remodeling of beta cells has been observed in both experimental animals and samples from humans with type 1 and type 2 diabetes." (PMID 40600018, 2025). "Moreover, PFKFB3 is overexpressed in pancreatic islets from individuals with type 2 diabetes." (PMID 40600018, 2025).
autoimmune disease (3 papers, 2021 to 2022). A disorder resulting from loss of function or tissue destruction of an organ or multiple organs, arising from humoral or cellular immune responses of the individual to their own tissue constituents. "PFKFB3 deficiency can cause the energy-deprived and autophagy-deficient, apoptosis-sensitive T-lymphocytes which are characteristic of autoimmune disease." (PMID 34163485, 2021). "Several of these genes such as IL2RA and PFKFB3 have previously been implicated in the development of autoimmune diseases or play a role in critical T cell pathways, suggesting these genes are likely targets that explain the molecular function of the risk variants." (PMID 35773720, 2022). "Irrespective of this, two candidate causal SNPs and genes including rs3087243 (RAPH1) and rs61839660 (IL2RA, RBM17, PFKFB3, LINC02649) were found to be common between T1D and other autoimmune diseases." (PMID 35773720, 2022).
Cerebral ischemia (3 papers, 2019 to 2023). Restriction of arterial blood supply to the brain associated with insufficient oxygenation to support the metabolic requirements of the tissue. "Furthermore, we show that in vivo administration of this PFKFB3 inhibitor protects against motor discoordination, neurological deficiency and brain damage in a mouse model of brain ischemia/reperfusion." (PMID 31406177, 2019). "LncRNA GAS5 can bind to the PFKFB3 promoter to promote PFKFB3 expression to foster neuronal glycolysis, and this aggravates cerebral ischemia/reperfusion injury." (PMID 33040050, 2020). "In the cerebral ischemia/reperfusion (CI/R) model, YY1 binds to lncRNA GAS5 to form a complex that fosters PFKFB3 transcription, glycolysis, and neuronal apoptosis." (PMID 37184686, 2023).
clear cell renal cell carcinoma (3 papers, 2021 to 2024). "PFKFB3 expression levels were analyzed in clear cell renal cell carcinoma (ccRCC) tissues, together with its relationship with clinical characteristics of ccRCC." (PMID 35057732, 2022). "ARNT was recently found upregulated in clear cell renal cell carcinoma: its expression was responsible for cell migration/invasion and, coherently with our data also for the regulation of glycolytic enzymes like PFKFB3, (6−phosphofructo−2−kinase/fructose−2,6−bisphosphatase 3) and HK2 (hexokinase-2)." (PMID 35251951, 2021).
colon adenocarcinoma (3 papers, 2014 to 2023). "PFKFB3 expression is high in colon adenocarcinomas and we thus initially transfected HCT-116 colon adenocarcinoma cells with PFKFB3-specific siRNA and confirmed selective suppression of PFKFB3 relative to cells transfected with a control siRNA." (PMID 24451478, 2014).
diabetic kidney disease (3 papers, 2022 to 2026). Progressive kidney disorder caused by vascular damage to the glomerular capillaries, in patients with diabetes mellitus. "PFKFB3 expression was upregulated in endothelial cells exposed to high glucose conditions and contributed to diabetic kidney disease by enhancing ECM production by interacting with TGF-β." (PMID 37480086, 2023).
E. coli infection (3 papers, 2018 to 2023). "Interestingly, many genes involved in glycolysis were upregulated by E. coli infection in both Mkp-1+/+ and Mkp-1−/− mice, including pyruvate dehydrogenase kinase (Pdk) 3/4, and 6-phosphofructo-2-kinase/fructose-2,6-biphosphatase 3 (Pfkfb3)." (PMID 30563203, 2018). "As for the eight common genes screened out in all four datasets, CEACAM1, GK, PFKFB3, and TNFAIP6 emerged repeatedly in the S. aureus group, but CEACAM1, IL18RAP, LILRA5, PFKFB3, PSTPIP2, and SOCS3 emerged in the E. coli infection." (PMID 31093495, 2019).
endometrial cancer (3 papers, 2021 to 2023). Primary or metastatic malignant neoplasm involving the endometrium (mucous membrane that lines the endometrial cavity). "Inhibition of PFKFB3 in endometrial cancer cells → inhibition of glycolysis, suppression of proliferation, increased sensitivity and DNA damage to chemotherapeutics, increased cell death." (PMID 37190033, 2023).
esophageal cancer (3 papers, 2021 to 2025). A primary or metastatic malignant neoplasm involving the esophagus. "Our study demonstrates that the loss of PFKFB3 increased 5-FU resistance in esophageal cancer cell lines, which we successfully validated in three human esophageal cancer cell lines: KYSE-70, KYSE-270, and KYSE-150." (PMID 40427135, 2025). "For example, lncRNA AGPG increases the stability of PFKFB3 by inhibiting ubiquitination at Lys302 and subsequent proteasomal-dependent degradation of PFKFB3 and activates glycolytic flux, causing metabolic reprogramming in esophageal cancer cells." (PMID 34560889, 2021). "So why is there an increase in 5-FU resistance in cancer cells after PFKFB3 knockout in esophageal cancer cell lines?" (PMID 40427135, 2025). "To explore the relationship between PFKFB3 and 5-FU resistance, we initially knocked out PFKFB3 in three human esophageal cancer cell lines (KYSE-70, KYSE-270, KYSE-150)." (PMID 40427135, 2025). "Our cell cycle results indicate that the effect of PFKFB3 knockout on the S phase of the cell cycle varies among the three esophageal cancer cell lines." (PMID 40427135, 2025). "The findings indicate that the knockout of PFKFB3 resulted in increased resistance to 5-FU in these three human esophageal cancer cell lines." (PMID 40427135, 2025). "Our results show that in the absence of 5-FU treatment, no significant changes were observed between the WT cells and the PFKFB3 knockout cells in all three esophageal cancer cell lines." (PMID 40427135, 2025). "In order to explore the mechanism behind the increased resistance to 5-FU after PFKFB3 knockout, we first utilized flow cytometry with Annexin V-APC/PI staining to detect the apoptosis status of esophageal cancer cells before and after 5-FU treatment." (PMID 40427135, 2025).
fungal infection (3 papers, 2021 to 2025). "The risk genotype impaired the expression of PFKFB3 by human macrophages in response to fungal infection, which was correlated with a defective activation of glycolysis and the ensuing antifungal effector functions." (PMID 34044589, 2021). "Our data disclose a genetic variant associated with defective activation of PFKFB3 following fungal infection." (PMID 34044589, 2021). "To figure out the exact regulatory function of PFKFB3 in fungal infections, we intervened in its expression." (PMID 41425966, 2025). "This study reveals the involvement of PFKFB3 in modulating corneal inflammation following fungi infection." (PMID 41425966, 2025). "Collectively, these findings demonstrate the important contribution of genetic variation in PFKFB3 to the risk of IPA in patients undergoing HSCT and support its inclusion in prognostic tools to predict the risk of fungal infection in this clinical setting." (PMID 34044589, 2021). "Importantly, genetic variation in PFKFB3 is correlated with differential production of IL-1β after fungal infection, suggesting the existence of bidirectional signaling events, in which PFKFB3 may also be able to regulate the activation of the NLRP3 inflammasome to drive the production of IL-1β." (PMID 34044589, 2021).
myocardial ischemia (3 papers, 2016 to 2023). A disorder of cardiac function caused by insufficient blood flow to the muscle tissue of the heart. "Subsequently, mice were insulted with in situ myocardial ischemia-reperfusion to assess the functional role of myocardial-specific PFKFB3 in pinocembrin-afforded cardioprotection." (PMID 33178386, 2020). "Additionally, it increased glycolysis by activating the NF-κB/PFKFB3 signaling pathway during myocardial ischemia." (PMID 38114486, 2023).
non-small cell lung carcinoma (3 papers, 2013 to 2023). A group of at least three distinct histological types of lung cancer, including non-small cell squamous cell carcinoma, adenocarcinoma, and large cell carcinoma. "In ALK (anaplastic lymphoma kinase)-positive non-small cell lung cancer, PFKFB3 is a downstream molecule of ALK-STAT3 signaling pathway that positively regulates the glycolysis level and plays a carcinogenic role in tumor cells." (PMID 36973739, 2023). "The highest percentage of candidate fusion transcripts of AL137145.2-6-phosphofructo-2-kinase/fructose-2, 6-biphosphatase 3 (PFKFB3) was found in non-small cell lung cancer." (PMID 34336943, 2021).
oral cancer (3 papers, 2021 to 2025). "In oral cancer patients, we found that co-expressions of high PFKFB3/low p27 or high PFKFB3/high cyclin B1 or Slug were associated with poor DSS." (PMID 37919747, 2023). "In addition, high PFKFB3 expression was also associated with poor DSS in oral cancer patients with moderate or poor cell differentiation, lymph node metastasis, and larger tumors.." (PMID 37919747, 2023). "In addition, high PFKFB3 expression was associated with a shorter survival in oral cancer patients with poor cell differentiation, large tumors, and larger tumor sizes." (PMID 37919747, 2023). "The co-expressions of PFKFB3/cell cycle or EMT markers and PFKFB4/stemness markers were associated with poor prognosis in oral cancer patients." (PMID 37919747, 2023). "Our results indicate that PFKFB3 was highly expressed in OSCC tissues and associated with a poor OS in oral cancer patients." (PMID 37919747, 2023). "The overexpression of PFKFB3 and PFKFB4 was associated with low survival in oral cancer patients and was involved in cell growth/migration and chemoresistance/cancer stemness in OSCC cells, respectively." (PMID 37919747, 2023). "We found that high PFKFB3 expression was associated with a short PFI in patients with larger tumor size (T3 and T4) and was associated with a short DFI in oral cancer patients with lymph node metastasis (N1, N2 and N3)." (PMID 37919747, 2023). "However, if PFKFB3 is involved in cell growth through the regulation of NF-kB signaling in oral cancer, this topic will require further study." (PMID 37919747, 2023). "We found that oral cancer patients with high expression of PFKFB3 and PFKFB4 had poor prognosis." (PMID 37919747, 2023). "We discovered that PFKFB3 expression in tumor tissues was slightly higher than that in tumor adjacent normal tissues but that PFKFB4 expression was significantly higher in the tumor tissues of oral cancer patients." (PMID 37919747, 2023). "Furthermore, oral cancer patients with co-expressions of PFKFB3/cell cycle or EMT markers and PFKFB4/stemness markers had poor prognosis." (PMID 37919747, 2023). "Our results suggest that oral cancer patients with higher PFKFB3 expression exhibits lymph node metastasis, implying that PFKFB3 might promote lymphangiogenesis for lymph node metastasis." (PMID 37919747, 2023). "Our current study supports the clinical relevance and biological functions of PFKFB3 and PFKFB4 in oral cancer." (PMID 37919747, 2023). "The co-expressions of PFKFB3/cell cycle or EMT markers and PFKFB4/stemness markers in oral cancer patients were also related to poor prognosis." (PMID 37919747, 2023). "Our results indicate that PFKFB3 and PFKFB4 expression levels have different effects on the prognosis of oral cancer patients with different clinicopathological outcomes." (PMID 37919747, 2023). "High PFKFB3 and PFKFB4 expression had different effects on the prognosis of oral cancer patients with different clinicopathological outcomes." (PMID 37919747, 2023).
osteoarthritis (3 papers, 2020 to 2025). A noninflammatory degenerative joint disease occurring chiefly in older persons, characterized by degeneration of the articular cartilage, hypertrophy of bone at the margins and changes in the synovial membrane. "The overexpression of PFKFB3 in osteoarthritis promotes the survival of cartilage tissues and chondrocytes via the PI3K/AKT/CHOP signaling pathway, thereby conferring protective effects on cartilage." (PMID 41425966, 2025).
prostate carcinoma (3 papers, 2013 to 2019). A carcinoma that arises from epithelial cells of the prostate gland. "Most published results have reported that the PFKFB gene over-expressed in cancer is PFKFB3, although, as noted, a recent result was cited that indicated over-expression of PFKFB4 in three different prostate cancer cell lines." (PMID 25859558, 2015).
acute lung injury (2 papers, 2021 to 2022). A condition of lung damage that is characterized by bilateral pulmonary infiltrates (pulmonary edema) rich in neutrophils, and in the absence of clinical heart failure. "A growing number of studies have shown that PFKFB3 is enhanced in various inflammatory or immune-related diseases, such as acute lung injury, myocardial dysfunction, and cancer." (PMID 36589684, 2022).
acute pancreatitis (2 papers, 2024 to 2025). An acute inflammatory process that leads to necrosis of the pancreatic parenchyma. "Our findings identify PFKFB3 as a critical therapeutic target for treating glucose metabolism disorders in acute pancreatitis." (PMID 40618046, 2025). "The use of PFKFB3 inhibitors delivered through cell membrane nanovesicles offers a promising new approach to treating acute pancreatitis (AP)." (PMID 40618046, 2025).
adenoma (2 papers, 2023 to 2024). A neoplasm arising from the epithelium. "We found that in adenoma and carcinoma, the expression of the number of gene activation is generally more than the number of gene expression suppression and four kinds of DEG eventually involve PFKFB3, which aroused our interest." (PMID 38098990, 2023).
Alzheimer disease (2 papers, 2019 to 2025). A progressive, neurodegenerative disease characterized by loss of function and death of nerve cells in several areas of the brain leading to loss of cognitive function such as memory and language. "Scatter plots and forest plots further supported a positive causal relationship between PFKFB3 and Alzheimer’s disease." (PMID 41195067, 2025).
Anxiety (2 papers, 2024 to 2025). Intense feelings of nervousness, tension, or panic often arise in response to interpersonal stresses. "The open-field test revealed fear and/or anxiety in CamkIIα-Pfkfb3 mice." (PMID 38789798, 2024). "Interestingly, behavioural alterations including motor discoordination, fear and/or anxiety and cognitive impairment were corrected by restoring brain NAD+ levels in NMN-treated Pfkfb3-expressing mice." (PMID 38789798, 2024).
Arthritis (2 papers, 2019 to 2021). Inflammation of a joint. "Importantly, inhibition of the glycolytic activity of 6-phosphofructo-2-kinase/fructose-2, 6-bisphosphatase 3 (PFKFB3) not only impaired cytokine secretion and decreased cell proliferation and migration of RASFs, but also ameliorated the onset and severity in an arthritis model." (PMID 30944034, 2019).
aspergillosis (2 papers, 2021 to 2024). Aspergillosis is an infection, growth, or allergic response caused by the Aspergillus fungus. "Additionally, increased susceptibility to aspergillosis has been observed in hematopoietic stem cell transplant patients with gene variants in TLR4, plasminogen, PFKFB3 polymorphisms, and other genetic factors." (PMID 39728022, 2024).
autoimmune (2 papers, 2017 to 2022). "This strongly linked the region to metabolic and autoimmune conditions through variation in T cell transcription and lends relevance to the transcriptional control in the PFKFB3 gene region for the development of autoimmune conditions." (PMID 36425763, 2022). "Also, modulation of activity and expression of PFKFB3 in autoreactive T cells has been shown to ameliorate disease, suggesting PFKFB3 as a potential therapeutic target for autoimmunity." (PMID 28426686, 2017).
bladder cancer (2 papers, 2021 to 2025). "Our current results suggest that TAZ is vital for glycolysis in bladder cancer cells and functions by regulating the expression of PFKFB3, HK2 and GLUT1, which serve as key components in glycolysis." (PMID 33499877, 2021).
brain tumors (2 papers, 2021 to 2023). "High PFKFB3 expression is linked to poor survival in brain tumors." (PMID 34831136, 2021). "Moreover, high PFKFB3 expression is linked to poor survival in brain tumors, indicating that PFKFB3 might be a therapeutic target for various types of cancer." (PMID 37919747, 2023). "Solitary or concomitant PFKFB3 inhibition has additionally shown great potential in restoring chemosensitivity and radiosensitivity in treatment-resistant brain tumors." (PMID 34831136, 2021). "An improved understanding of canonical and non-canonical functions of PFKFB3 could allow for the development of effective combinatorial targeted therapies for brain tumors." (PMID 34831136, 2021).